HNRNPC (heterogeneous nuclear ribonucleoprotein C)
Diseases named in the same sentence as HNRNPC in open-access papers (continued):
Sharing a sentence is not in itself a finding about the gene and the disease.
head and neck squamous cell carcinoma (9 papers, 2020 to 2025). A squamous cell carcinoma that arises from any of the following anatomic sites: lip and oral cavity, nasal cavity, paranasal sinuses, pharynx, larynx, and salivary glands. "It is reported that RBMX and HNRNPC can predict the prognosis of head and neck squamous cell carcinoma and are related to immune infiltration." (PMID 37194014, 2023). "In head and neck squamous cell carcinoma (HNSCC), METTL3 and HNRNPC were highly expressed in tumor tissue than normal tissue, high expression of METTL3 and HNRNPC were positively associated with the infiltration of CD4 naive T cells, CD4 memory-activated T cells, and eosinophils." (PMID 35296338, 2022). "However, a similar study on head and neck squamous cell carcinoma (HNSCC) showed that HNRNPC and YTHDC2 are independent prognostic factors for HNSCC, and the risk score is related to age, gender, stage, and grade." (PMID 34631545, 2021). "In head and neck squamous cell carcinoma (HNSC), the presence of HNRNPC, DNMT1, DNMT3A, ZC3H13, NSUN5, and IGF2BP2 highlights potential cross-talk between DNA and RNA methylation in immune modulation." (PMID 40565233, 2025).
liver cancer (9 papers, 2022 to 2025). An epithelial or non-epithelial malignant neoplasm that arises from the liver. "Through further immunofluorescence analysis of subcutaneous tumor tissues from liver cancer cells, we validated findings that HNRNPC expression is closely associated with levels of tumor-infiltrating immune cells." (PMID 39735682, 2025). "As expected, hnRNPC overexpression caused an increase in both isomiR-21-5p | ±1 expression and the isomiR ratio in all tested liver cancer cell lines." (PMID 35729324, 2022). "Suppressing hnRNPC significantly curtailed the proliferation, metastasis, and infiltration of liver cancer cells." (PMID 41429980, 2025). "In summary, our findings highlight HNRNPC as a prognostic marker in various cancers, including liver cancer, and suggest its involvement in shaping the tumor immune microenvironment." (PMID 39735682, 2025). "We validated the distinct expression patterns of HNRNPC in liver cancer compared to normal liver tissue through immunohistochemistry data from the HPA database." (PMID 39735682, 2025). "The anti-growth effect of hnRNPC inhibition was mostly rescued by the introduction of isomiR-21-5p | ±1 mimics in all the tested liver cancer cell lines." (PMID 35729324, 2022). "Consistent with previous findings, HNRNPC was significantly overexpressed in liver cancer." (PMID 39735682, 2025). "Survival analysis revealed robust associations between HNRNPC expression levels and disease-specific survival (DSS), overall survival (OS), progression-free survival (PFS), and disease-free survival (DFS) in patients with liver cancer (p = 3.2e-4, p = 6.5e-3, p = 1.1e-3, and p = 0.02, respectively)." (PMID 39735682, 2025). "Interestingly, it was recently reported that heterogeneous nuclear ribonucleoprotein C (hnRNPC) could directly interact with pri-miR-21 to induce an isoform shift of miR-21 in liver cancer cells." (PMID 36139366, 2022). "Moreover, we demonstrate that heterogeneous nuclear ribonucleoprotein C (hnRNPC) physically interacts with primary miR-21 (pri-miR-21) to induce isomiR-21-5p | ±1, highlighting the potential therapeutic value of targeting the hnRNPC-isomiR-21-5p | ±1 regulatory axis in the treatment of liver cancer." (PMID 35729324, 2022). "Both the isomiR-21-5p | ±1 level and isomiR ratio were significantly reduced in both hnRNPC and U2AF2 knockdown cells compared to controls in all tested liver cancer cell lines." (PMID 35729324, 2022). "To validate this hypothesis, we used RNA interference to knockdown hnRNPC and U2AF2 expression in liver cancer cells, after which miR-21-5p and isomiR-21-5p | ±1 expression levels were measured." (PMID 35729324, 2022). "Our findings suggest an oncogenic function for the non-canonical isomiR-21-5p | ±1 in liver cancer, and its production was shown to be regulated by hnRNPC." (PMID 35729324, 2022). "Therefore, we hypothesized that hnRNPC and/or U2AF2 binding to pri-miR-21 modulates the Drosha cleavage sites in pri-miR-21 to produce more isomiR-21-5p | ±1 in liver cancer." (PMID 35729324, 2022).
ovarian carcinoma (9 papers, 2019 to 2022). A malignant neoplasm originating from the surface ovarian epithelium. "GSEA analysis demonstrated that the expressions of METTL3, YTHDC1, RBM15B, HNRNPC, IGF2BP2, RBMX, and ZC3H13 were correlated with a higher number of multiple Hallmark pathways in ovarian cancer." (PMID 33225598, 2021). "Additionally, it was discovered that Taxol had a greater effect on ovarian cancers with elevated HNRNPC expression in the survival curve." (PMID 35344508, 2022). "hnRNPC is a survival-related splicing factor in OSCC, and served as the tumor facilitator in non-small cell lung cancer, ovarian cancer." (PMID 32549791, 2020). "Furthermore, HNRNPC, CRNKL1, PNN and PPIE were also reported to have a high expression and biological function in several cancers including ovarian cancer 21-24." (PMID 33437214, 2021). "Two GEO databases demonstrated that 7 readers (HNRNPC, IGF2BP1, IGF2BP2, IGF2BP3, RBMX, YTHDC2, and YTHDF2) and 3 writers (METTL3, RBM15, and RBM15B) were more highly expressed in ovarian cancer than in ovarian surface epithelium or normal peritoneum tissues (GEO14407 and GEO12470)." (PMID 33225598, 2021). "Moreover, miR-744-5p was reported to facilitate cell apoptosis by targeting HNRNPC and NFIX in ovarian cancer.In this study, CDCA4 was identified as the target gene of miR-744-5p and was negatively regulated by miR-744-5p." (PMID 34090440, 2021).
prostate carcinoma (9 papers, 2019 to 2025). A carcinoma that arises from epithelial cells of the prostate gland. "Further analysis revealed a significant difference in the five-year survival rate of prostate cancer patients based on HNRNPC expression (p < 0.0053)." (PMID 38438956, 2024). "The expression of HNRNPC in primary prostate cancer with metastasis or castration-resistant prostate cancer samples was even higher than that in localized prostate cancer." (PMID 38438956, 2024). "Analysis of the GEO dataset showed that HNRNPC was significantly upregulated in prostate cancer samples compared to normal samples." (PMID 38438956, 2024). "We screened and identified HNRNPC, a critical gene that promotes prostate cancer development, through ultrasound image features in combination with proteomics." (PMID 38438956, 2024). "We found that the CNVs patterns of HNRNPC, METTL3, RBM15, ALKBH5 and FTO (one reader, two writers, and two erasers) were notably associated with RFS of prostate cancer." (PMID 32710725, 2020). "Specifically, copy number loss of HNRNPC, METTL3, and FTO were significantly correlated with poor survival of prostate cancer, while patients with copy number gain of RBM15 and ALKBH5 had worse RFS." (PMID 32710725, 2020). "Furthermore, HNRNPC expression is negatively correlated with the levels of most immune cell infiltration in prostate cancer." (PMID 39028290, 2024). "It has been found that silencing heterogeneous nuclear ribonucleoprotein C (HNRNPC) can inhibit the proliferation and metastasis of prostate cancer cells." (PMID 39028290, 2024).
endometriosis (8 papers, 2020 to 2025). The growth of functional endometrial tissue in anatomic sites outside the uterine body. "Both HNRNPA2B1 and HNRNPC were associated with the severity of endometriosis in eutopic samples, and also exhibited diagnostic potential for endometriosis." (PMID 33232273, 2020). "Another study showed the abnormal expression of m6A regulators in endometriosis and indicated that hnRNPA2B1 and hnRNPC might be correlated with immune response, serving as useful diagnostic biomarkers for endometriosis." (PMID 36632456, 2023). "Furthermore, HNRNPA2B1 and HNRNPC that are m6A RNA-binding proteins were demonstrated to serve as useful diagnostic biomarkers for endometriosis." (PMID 35755020, 2022). "It is likely that these changes in the expression of HNRNPA2B1 and HNRNPC are associated with the abnormal immune response and that these factors may serve as efficient m6A-related diagnostic biomarkers in endometriosis." (PMID 33232273, 2020). "HNRNPA2B1 and HNRNPC are involved in the regulation of immune responses, and their abnormal expression is closely related to the pathogenesis of endometriosis." (PMID 40356909, 2025). "Down-regulated METTL3, heterogeneous nuclear ribonucleoprotein C (HNRNPC), and A2/B1 (HNRNPA2B1) have been linked to the development of endometriosis." (PMID 37891533, 2023). "Until now, the role of HNRNPC in endometriosis remained unclear, while the protein levels of HNRNPA2B1 were revealed to be downregulated in endometriosis." (PMID 36672827, 2022). "Abnormalities in the gene transcription factors network associated with endometriosis might affect the expression of HNRNPA2B1 and HNRNPC." (PMID 33232273, 2020). "Three m6A regulators (HNRNPC, HNRNPA2B1, and FTO) were identified as being significantly overexpressed in endometriosis patients and were visualized utilizing a boxplot." (PMID 36672827, 2022). "Many studies have shown that the pathogenesis of endometriosis may be related to m6A, and some of these regulators, including METTL3, YTHDF2, YTHDF3, HNRNPC, HNRNPA2B1, and FTO, are significantly dysregulated in the ectopic endometrium." (PMID 40356909, 2025). "For example, the first investigation into how m6A regulators function in endometriosis indicated that m6A regulators in endometriosis, such as METTL3, YTHDF2, YTHDF3, HNRNPC, HNRNPA2B1, and FTO, are significantly dysregulated compared with normal endometrial tissue." (PMID 36894952, 2023). "In conclusion, we observed significant dysregulation of m6A regulators in endometriosis, and found that HNRNPA2B1 and HNRNPC might correlate with the immune response and serve as useful diagnostic biomarkers for endometriosis." (PMID 33232273, 2020). "Another study has also identified three different m6A regulators (FTO, HNRNPC, and HNRNPA2B1) between the endometriosis and non-endometriosis groups." (PMID 37891533, 2023).
pancreatic cancer (8 papers, 2021 to 2025). "High expression of heterogeneous nuclear ribonucleoprotein C (HNRNPC) in pancreatic cancer is associated with metastasis and poor prognosis." (PMID 40448344, 2025). "The rs7495G allele increased the risk of pancreatic cancer by promoting the expression of heterogeneous nuclear ribonucleoprotein C (hnRNPC), which is a m6A reader." (PMID 35220962, 2022). "Furthermore, the rs7495G allele in the hnRNPC gene promotes hnRNPC expression by disrupting a putative binding site for miR-183-3p in pancreatic cancer." (PMID 34239358, 2021). "As a result, the goal of this study is to better understand the molecular role of hnRNPC in patients with PDAC, which will allow for the identification of new possible diagnostic and therapy techniques for pancreatic cancer patients." (PMID 35355828, 2022). "Remarkably, we observed that hnRNPC, an RBP, is highly expressed in PDAC and is associated with poor prognosis in pancreatic cancer." (PMID 35355828, 2022). "In this study, we identified that hnRNPC regulates pancreatic cancer tumorigenesis by binding and stabilizing IQGAP3, and thus, this study allows identification of novel diagnostic markers and potential targets to develop treatment strategies for pancreatic cancer." (PMID 35355828, 2022). "However, relatively less is known about the involvement of hnRNPC in pancreatic cancer." (PMID 35355828, 2022). "To understand the role of hnRNPC in PDAC, we assessed its expression levels in various human pancreatic tumor cell lines such as PANC-1, MIApaca-1, SW1990, and BxPC-3 with a respective control (HPNE)." (PMID 35355828, 2022). "Here, gemcitabine-resistant pancreatic cancer cell lines and patient-derived xenograft (PDX) models are established, followed by high-throughput sequencing, which identified heterogeneous nuclear ribonucleoprotein C (HNRNPC) as a significantly upregulated factor in chemoresistant tumors." (PMID 41309519, 2025). "This is the first work to show that hnRNPC binds and stabilizes IQGAP3, allowing it to play an essential role in modulating PDAC proliferation, migration, invasion, and EMT, even though IQGAP3 was previously discovered to be increased in pancreatic cancer cell lines." (PMID 35355828, 2022).
bladder cancer (7 papers, 2021 to 2025). "The expressions of IGF2BP1, IGF2BP3, YTHDF1, YTHDF2, and HNRNPC were significantly up-regulated in bladder cancer." (PMID 40083693, 2025). "As the reader of m[superscript 6]A regulator genes, YTHDF1, YTHDF2 and HNRNPC were highly expressed in bladder cancer tissues compared with the normal tissues." (PMID 34521394, 2021). "rs5746136 regulated the expression levels of SOD2 by guiding the binding of hnRNPC to SOD2, which acted as a critical tumor suppressor by promoting apoptosis and inhibiting the proliferation, metastasis, and invasion of bladder cancer cells." (PMID 35220962, 2022).
lung squamous cell carcinoma (7 papers, 2021 to 2024). "HNRNPC expression is lower in the high risk group of patients with lung squamous cell carcinoma and is more sensitive to immunotherapy and chemotherapy." (PMID 39028290, 2024). "The expression level of HNRNPC was associated with TMB in several cancers, including STAD, LUAD, Lung Squamous Cell Carcinoma (LUSC), Skin Cutaneous Melanoma (SKCM), Thyroid Carcinoma (THCA), Thymoma (THYM)." (PMID 37469973, 2023). "Compared with the low-risk lung squamous cell carcinoma patients, the expressions of ALKBH5, METL3, HNRNPC, and KIAA1429 were significantly reduced in patients with high-risk lung squamous cell carcinoma." (PMID 34956201, 2021). "In lung squamous cell carcinoma, reduced KIAA1429, ALKBH5, METTL3, and HNRNPC expressions were predictive of better responses to chemotherapy and immunotherapy." (PMID 36831575, 2023).
lymph node metastasis (7 papers, 2020 to 2023). "HNRNPC expression was correlated with tumor stage, lymph node metastasis, and poor prognosis in oral squamous cell carcinoma." (PMID 37469973, 2023). "More importantly, the patients with high levels of HNRNPC had poor prognosis and correlated with tumor invasion and lymph node metastasis, demonstrating that HNRNPC was a poor prognostic biomarker for NSCLC." (PMID 36536402, 2022). "The expression of HNRNPC is abundant in LUAD tissues; it is significantly associated with age, sex, smoking history, race, lymph node metastasis, TNM stages, and low OS rates." (PMID 36061307, 2022). "Next, the m6A regulator HNRNPC was selected as the most influential predictor for NSCLC, and HNRNPC predicted poor prognosis and correlated with tumor invasion and lymph node metastasis." (PMID 36536402, 2022). "In addition, higher HNRNPC expression levels were positively correlated with advanced clinical stage and lymph node metastasis and meant undesirable overall." (PMID 32526707, 2020). "In TCGA cohort, HNRNPC was highly expressed in LUAD tissues and significantly related to age, sex, smoking history, ethnicity, lymph node metastasis, and TNM staging (P < 0.001)." (PMID 33569346, 2021).
melanoma (7 papers, 2015 to 2024). A malignant, usually aggressive tumor composed of atypical, neoplastic melanocytes. "Comparing primary melanoma and metastases, we found that ALKBH5, ELAVL1, FMR1, HNRNPA2B1, HNRNPC, IGF2BP1/2/3, KIAA1429, LRPPRC, RBM15, YTHDC1/2, YTHDF1/3, and ZC3H13 were significantly upregulated in metastases, while RBM15B and METTL3 were significantly upregulated in primary melanoma." (PMID 34993195, 2021).
colorectal cancer (6 papers, 2017 to 2025). A primary or metastatic malignant neoplasm that affects the colon or rectum. "In colorectal cancer, the prognostic value of the m6A RNA methylation regulators YTHDF1 and HNRNPC has been described." (PMID 34149792, 2021).
esophageal cancer (6 papers, 2020 to 2022). A primary or metastatic malignant neoplasm involving the esophagus. "We also found that a high level of HNRNPC was associated with poor prognosis in esophageal cancer patients." (PMID 34395102, 2021). "Among them, HNRNPC, a m6A regulator has been reported to be significantly correlated with worse outcomes and immune infiltration levels in esophageal cancer." (PMID 35627203, 2022). "Heterogeneous nuclear ribonucleoprotein C (HNRNPC), an RNA binding protein, was overexpressed in esophageal cancer tissues and cell lines." (PMID 34395102, 2021). "We further evaluated the expression pattern of HNRNPC in esophageal cancer cells and found that the expression level of HNRNPC in the KYSE30 and TE-1 cell lines was higher than that in the normal esophageal carcinoma epithelial cell line HEEC." (PMID 34395102, 2021). "The results showed that the low expression of ALKBH5 and the high expression of HNRNPC or WTAP were the best predictors for poor OS rates in esophageal cancer patients." (PMID 34395102, 2021). "We focused on the m6A-related gene HNRNPC and its role in esophageal cancer in light of our analysis of m6A-related gene expression levels and the prognostic values above." (PMID 34395102, 2021). "From the TCGA database, we found that several m6A-associated genes, including YTHDF1, HNRNPC, ZC3H13, YTHDC2, and METTL14 were dysregulated in esophageal cancer compared to matched normal tissues." (PMID 34395102, 2021). "Further, AK4, a radioresistant protein in esophageal cancer, was revealed in our study to bind with hnRNPC protein and its stability was enhanced by LINC00662." (PMID 32549791, 2020). "Our study further validated that HNRNPC was upregulated in esophageal cancer cell lines." (PMID 34395102, 2021). "We hypothesized that the candidate miRNA would be downregulated in esophageal cancer with a potential binding sequence for the 3′-UTR of HNRNPC." (PMID 34395102, 2021). "Also, given that HNRNPC was reported to interact with ZEB1 to stabilize its mRNAs in esophageal cancer, we therefore hypothesized that HNRNPC could possibly directly interact with ZEB1 mRNAs to prolong their stability in oral cancer cells." (PMID 35963855, 2022). "Our results indicated that HNRNPC may be the key m6A-related gene in esophageal cancer." (PMID 34395102, 2021). "Therefore, the results of the expression pattern and prognostic value of the m6A-related genes indicated that HNRNPC may be the key gene in m6A modification of esophageal cancer." (PMID 34395102, 2021). "Furthermore, silencing HNRNPC may also inhibit the migration and invasion of esophageal cancer cells." (PMID 34395102, 2021).
Obesity (6 papers, 2022 to 2025). Accumulation of substantial excess body fat. "Obesity also consistently altered 5 proteins in DMBA-exposed mice, including HNRNPC, HNRNPD, HSPA9, RPL36A, and KCTD12." (PMID 39910959, 2025). "Similar to RBM15, HNRNPC, and HNRNPA2B1, MYC expression level significance was also negatively related to obesity." (PMID 36120320, 2022).
oral squamous cell carcinoma (6 papers, 2020 to 2025). "Similarly, hnRNPC was identified as an independent prognostic biomarker in oral squamous cell carcinoma (OSCC) and the overexpression of hnRNPC facilitated the development of OSCC cells in vitro." (PMID 32898471, 2020). "LncRNA CYTOR regulates mitochondrial metabolism and glycolysis of oral cancer cells via HNRNPC-mediated ZEB1 stabilization in oral squamous cell carcinoma, and the level of CYTOR could be upregulated by forkhead box D1 to promote EMT and chemoresistance in oral squamous cell carcinoma." (PMID 36814556, 2023).